MDM2 (MDM2 proto-oncogene)
Diseases named in the same sentence as MDM2 in open-access papers (continued):
Sharing a sentence is not in itself a finding about the gene and the disease.
sarcoma (continued). "Overexpression of MDM2 has been shown to correlate positively with poor prognosis in sarcoma, glioma and acute lymphocytic leukemia." (PMID 21504625, 2011). "A further 56 genes were altered in two melanomas, but the only known cancer-related gene was MDM2, an oncogene previously demonstrated to be amplified in sarcoma, glioma, colorectal and other cancers including melanoma." (PMID 21494657, 2011). "Altered regions included known targets, such as CDK4 (cyclin-dependent kinase 4) and SAS (sarcoma amplified sequence), as well as MDM2 (mouse double minute 2 homolog), for 12q14.1 and 12q15 amplifications, respectively." (PMID 20444257, 2010). "Together, this work elucidates MDM2's central role in pediatric sarcoma pathogenesis and presents dCDK9-010 as a first-in-class, MDM2-recruiting P-TEFb degrader and an exemplary MDM2-TEMAD that enables precise targeting of MDM2-dependent oncogenic transcriptional addiction." (PMID 42318649, 2026). "Additionally, two patients received a positive MDM2 fluorescence in situ hybridization (FISH) to confirm an intimal sarcoma diagnosis." (PMID 40571919, 2025). "Intimal sarcoma represents an undifferentiated sarcoma, characterized by MDM2 gene amplification." (PMID 40506961, 2025). "MDM2 co-expression in our case suggested sarcoma initially, necessitating ALK-FISH confirmation." (PMID 40917711, 2025). "The results of this clinical trial will determine whether the standard clinical practice for treating DDLPS and potentially other sarcomas characterized by MDM2 overexpression can be improved." (PMID 38275873, 2024). "MDM2 amplification has been reported in some gliomas, carcinomas, and hematological neoplasms, but this characteristic is much more frequently observed in sarcomas." (PMID 38275873, 2024). "Currently, the focus is on defining sarcomas based on their histologic subtype, molecular profile and genetic changes, rather than their anatomic origin, which will aid the development of novel therapies, like MDM2 and CDK4/6 inhibitors." (PMID 37888062, 2023). "Moreover, the MDM2 gene was found to be considerably elevated in various cancers, including invasive bladder cancer, kidney cancer, leukemia, lymphoma, and sarcoma." (PMID 37049742, 2023). "Studies have shown that over 90% of these sarcomas have MDM2 amplification." (PMID 37240900, 2023).
sarcoma (continued). "Conversely however, Guellec et al26 described 2‐year overall survival rates for UPS with MDM2 amplification, conventional DDLPS, and UPS without MDM2 expression of 93.3%, 90.7%, and 73.9%, respectively, thus indicating that MDM2 amplified sarcomas showed a better prognosis." (PMID 37395142, 2023). "This could lead to improved treatment outcomes for sarcoma and other cancers in which p14ARF and MDM2 play a role." (PMID 37297833, 2023). "Copy-number alterations in sarcomas are relatively uncommon, except for MDM2 amplification." (PMID 37627196, 2023). "Although the expression of CNTNAP4 in this dataset had lowly expressed transcripts, the levels of CNTNAP4 interacting genes (MACF1, MLLT4, FBXO21, CASK) were found to be highly enriched in the Ki67high sarcoma cells, which was found as well to cluster with high MDM2 expression." (PMID 36599925, 2023). "Also, some other sarcomas indicate MDM2 amplification at a very low rate in cancer cells, including malignant peripheral nerve sheath tumors and conventional osteosarcomas." (PMID 35145371, 2022). "In general, MDM2 amplification is seen in 7% of human cancers and one-third of all sarcomas." (PMID 36230502, 2022). "However, MDM2 amplification can also be seen in other sarcomas, and hence interpretation of the results has to be done in the appropriate clinical context, especially when dealing with small biopsy samples." (PMID 35887151, 2022). "Taken together, p14ARF epigenetic silencing might represent a valuable target for affecting MDM2 function in sarcoma." (PMID 36439412, 2022). "In conclusion, the story of MDM2 in sarcomas gives us insight into ‘M’olecular mechanisms." (PMID 33799733, 2021). "Interestingly, when low-grade central or parosteal osteosarcoma dedifferentiate into a high-grade sarcoma, they retain their MDM2/CDK4 amplification and overexpression." (PMID 33799733, 2021). "Although this a small study, we show that FLT may be used to predict responses to c-MET inhibitor or MDM2 inhibitor in diverse sarcoma sub-types." (PMID 32106426, 2020). "Likewise, transgenic mice overexpressing MDM2 are more prone to spontaneous tumor development, specifically sarcoma and lymphoma." (PMID 31905981, 2019). "The high rate of MDM2 amplification is consistent in human and mice sarcomas." (PMID 30816344, 2019). "In summary, co-overexpression of MDM2 and CDK4 causes high-grade sarcoma with a DDLLPS-like morphology in transformed human BMSCs by accelerating cell growth and migration, and the blockage of adipogenic potential, after cooperation with multiple genetic factors." (PMID 31160689, 2019). "Upregulation of MDM2 has also been observed in a variety of sarcoma." (PMID 29651441, 2018). "The highest prevalence of MDM2 amplification by histologic type was found in sarcoma patients (13 of 33 = 39% vs 10 of 114 non-sarcoma patients = 9%; p < 0.0001); the second highest was found in patients with metastatic breast cancer (3 of 56 = 5.3% vs 20 of 91 = 22%; p = 0.0071)." (PMID 30237864, 2018). "Previous studies have suggested that the presence of neochromosomes in cancer and sarcoma in particular, could explain the mechanism of MDM2 amplification in these tumors." (PMID 30237864, 2018). "Indeed, small molecules have recently been evaluated in clinical trials in mdm2‐amplified sarcomas with partial success; more than half of patents exhibiting “stable” disease." (PMID 27273042, 2016).
sarcoma (continued). "MDM2 amplification is one of the most frequently observed recurrent gene amplifications in The Cancer Genome Atlas pan-cancer analyses of copy-number variations, and in particular sarcomas." (PMID 24321497, 2013). "Therefore, it remains uncertain if the tumor that Watkin described was a DL or a pleomorphic sarcoma with MDM2 amplification." (PMID 22924136, 2012). "Early studies suggest that MDM2 antagonists may be particularly effective in sarcomas because MDM2 is frequently amplified in these tumours." (PMID 21624110, 2011). "Our in vitro data suggest that MDM2 antagonists could offer effective therapy for sarcoma either as single agent or in combination with prevailing chemotherapy, and may significantly reduce the genotoxic burden with the same or better antitumour effect." (PMID 21624110, 2011). "However, the majority of human sarcomas have normal level of MDM2 and the therapeutic potential of MDM2 antagonists in this group is still unclear." (PMID 21624110, 2011). "The MDM2 protein is known to be overexpressed in some sarcomas including rhabdomyosarcoma." (PMID 11742497, 2001). "According to the WHO Classification of Soft Tissue Tumors, essential diagnostic criteria include the transition of ALT to spindle, pleomorphic, non-lipogenic low or high-grade sarcomas, while desired diagnostic criteria include the expression of MDM2 or demonstration of MDM2 gene amplification." (PMID 39036280, 2024).
sarcoma (continued). "MDM2 positivity on immunohistochemistry is specific to DDLPS and aids in differentiating it from other sarcomas and GISTs." (PMID 41509081, 2026). "Remarkably, the transcriptional effects of P-TEFb degradation by dCDK9-010 are phenocopied by MDM2-mediated BET degradation, resulting in potent anti-sarcoma efficacy alongside a favorable therapeutic index and minimal toxicity in nonmalignant cells." (PMID 42318649, 2026). "Some sarcomas have specific molecular characteristics, such as SYT::SSX fusion in synovial sarcoma, EWSR1::FLI1 fusion in Ewing's sarcoma (ES), and MDM2 amplification in dedifferentiated liposarcoma (DDLS), leading to correct diagnosis and treatment." (PMID 40755265, 2025). "On the other hand, the specificity of MDM2 and CDK4 was relatively low, as some sarcomas, including myxofibrosarcoma and undifferentiated pleomorphic sarcoma, also show positivity." (PMID 40078181, 2025). "The standard procedure to identify a sarcoma includes the detection of this amplification through fluorescence in situ hybridization (FISH) and/or MDM2/CDK4 immunohistochemistry." (PMID 39687824, 2024). "MDM2 and DMC1 were significantly downregulated in HRDhigh sarcoma, but showed a sarcoma histotype‐specific expression." (PMID 36779660, 2023). "Because DDLS can mimic any type of sarcoma, MDM2 immunohistochemistry/FISH should be part of the panel of tests in any sarcoma occurring at any site, certainly if it is undifferentiated and pleomorphic, and so a FISH test to identify MDM2 was recommended." (PMID 37888062, 2023). "MDM2 immunohistochemistry and MDM2 amplification can help confirm a diagnosis of DDLPS and distinguish DDLPS from other undifferentiated sarcomas in the relevant clinical context." (PMID 36983010, 2023). "Gene amplifications are frequently present in sarcomas and were also identified in this study, namely CDK4 and MDM2 in 10.0% and 7.0% of cases, respectively." (PMID 36430703, 2022). "Principally, MDM2 and CDK4 examination allows differentiation of WDLPS from benign adipose tumors while in DDLPS, MDM2 and CDK4 evaluation help to exclude poorly differentiated sarcomas." (PMID 36230502, 2022). "Detection of MDM2 (and/or CDK4) amplification serves to distinguish DDL from other undifferentiated sarcomas." (PMID 34362013, 2021).
sarcoma (continued). "In this subtype of sarcoma, CDKN2A firmly connects to MDM2, CCND1, PIK3CA, CDK4, CBX7, and less firmly to EGFR, and IL-6." (PMID 34359782, 2021). "Out of the 12 sarcoma cfDNA samples, five sarcoma fusion genes (EWSR1-ATF1, MEAF6-PHF1, PAX3-FOXO1, EWSR1-FLI1, SS18-SSX2) and one MDM2 amplification were detected following analysis (50% of structural variants detected)." (PMID 33287361, 2020). "Recent clinical trials evaluating an MDM2 inhibitor (RG7112; a member of the Nutlin family) in sarcoma patients gave encouraging results with maintenance of stable disease." (PMID 27273042, 2016). "Copy-number amplification of MDM2 and MDM4 has also been specifically reported in Ewing’s Sarcoma, and co-amplification of both have been observed in a sub-set of sarcomas." (PMID 24321497, 2013). "Detection of amplification of MDM2 and/or CDK4 is potentially informative with respect to this sarcoma type." (PMID 24216705, 2013). "Expected alterations were identified in 97% (32/33) of the analyzed sarcomas: 11 with fusion genes, 10 with MDM2 amplifications, and 11 with non-specific SVs and CNVs." (PMID 40141463, 2025). "These genetic alterations closely resemble the genomic profile of other sarcomas that respond to CDK4/6 inhibition, suggesting a potential therapeutic strategy involving CDK4/6 inhibitors, either as a single agent or in combination with MDM2 inhibitors, for BCOR-fusion-positive sarcomas." (PMID 40001568, 2025). "The discovery of MDM2 over-expression in intimal sarcomas (as opposed to other histological subtypes) highlights the tumour signature at the molecular level, as it was first shown only a decade ago." (PMID 38732333, 2024). "It will therefore be important going forward, from a prognostic perspective, to distinguish intimal sarcomas with MDM2 amplifications from UPS, and this may serve as a basis for the application of MDM2 inhibitors as future therapies." (PMID 37395142, 2023). "Twenty-seven percent of the sarcomas with MDM2 expression lacked MDM2 amplification, and vice versa 45% of the tumors with gene amplification lacked MDM2 expression." (PMID 37821635, 2023). "It has been reported that undifferentiated pleomorphic sarcomas with MDM2 amplification are in fact DDLPS even in the absence of a well-differentiated LPS component." (PMID 36983010, 2023). "Our optimized method achieved 100% concordance for the HER2 FISH NordiQC - Quality Control 2015 evaluation, 100% concordance for genotyping and clerical accuracy for the sarcoma panel containing CHOP (DDIT3), FUS, EWSR1 and MDM2 in the UK NEQAS International Quality Expertise 2016 evaluation." (PMID 31236139, 2019). "Thus, our model showed that co-expression of MDM2 and CDK4 in transformed human BMSCs increases the tendency of high-grade sarcoma with a DDLPS-like morphology." (PMID 31160689, 2019).